PCSK9 (proprotein convertase subtilisin/kexin type 9)
Diseases named in the same sentence as PCSK9 in open-access papers (continued):
Sharing a sentence is not in itself a finding about the gene and the disease.
diabetes (continued). "Therefore, this study cannot provide data on potential effects of PCSK9 inhibitor therapy on glucose control, LDL-C and other parameters of the lipid panel as well as cardiovascular outcome in patients with insufficiently controlled diabetes mellitus." (PMID 33894772, 2021). "At least in our cohort of HCV patients, serum PCSK9 was not induced in patients with diabetes." (PMID 33920491, 2021). "In addition, most of the available real-world studies on PCSK9 inhibitors only investigated small groups of patients and did not specifically focus on patients with diabetes mellitus." (PMID 33894772, 2021). "After adjusting for age, sex, CVD, hypertension, obesity, and diabetes, SH patients who had been seen by cardiology had greater odds of being on any lipid‐lowering medication, high‐intensity statin, or PCSK9 inhibitor compared to those who had not been seen by cardiology." (PMID 33355940, 2021). "However, the currently available data from patients with anti-PCSK9 therapies do not show an increased incidence of diabetes." (PMID 33643060, 2021). "Furthermore, real-world evidence is substantially lacking investigating the efficacy of PCSK9 inhibitor therapy on LDL-C reduction in patients with diabetes." (PMID 33894772, 2021). "For example, a study has reported pharmacological treatments with PCSK9 inhibitors in patients with primary hypercholesterolemia resulted in increased fasting glucose levels compared to placebo but with no increase in the incidence of diabetes." (PMID 34380558, 2021). "We hypothesized that the effect of PCSK9 on vascular homeostasis may be mediated by EPCs in patients with or without type 2 diabetes mellitus (T2DM)." (PMID 33958634, 2021). "Indeed, there is currently no general agreement about the relationship between PCSK9 and diabetes, and further clarification is needed." (PMID 33302966, 2020). "PCSK9 concentration was not significantly related to smoking, hypertension or diabetes." (PMID 31711505, 2019). "However, it is important to note that when PCSK9 inhibitors and high-intensity statin combination therapy were compared with high-intensity statin monotherapy, the addition of PCSK9 inhibitors did not further increase the incidence of new diabetes." (PMID 41546841, 2026). "Additionally, PCSK9 inhibitors also demonstrate good efficacy and tolerability even in patients who are intolerant to statins, effectively lowering LDL-C levels without increasing the risk of new-onset diabetes." (PMID 41478627, 2025). "Furthermore, these findings are consistent with the results of major outcome trials such as FOURIER and ODYSSEY OUTCOMES, which reported no significant increase in diabetes or neurocognitive adverse events with PCSK9 inhibitor therapy, even at very low LDL-C levels." (PMID 40969933, 2025). "Additionally, because the evidence indicates there are no signs of worsening cognition or new onset diabetes, PCSK9 inhibitors may be a good option for patients who are particularly concerned about these ADEs with long-term statin use." (PMID 34869702, 2021). "Interestingly, PCSK9 inhibitors do not lead to an increased rate of new-onset diabetes." (PMID 29770231, 2018). "PCSK9-mAb receivers versus non-receivers were more likely to have CAD, less likely to have PAD, and less likely to have diabetes mellitus." (PMID 40760109, 2026). "The PCSK9 inhibitors are recommended for secondary prevention of MACE in patients with and without diabetes based on 15% RRR for cardiovascular death, MI, or stroke, as well as significant RRR in each component of the MACE composite, in separate trials." (PMID 34922811, 2022). "An intervention study assessing the effect of statin treatment on plasma PCSK9 and early EPC number in patients with and without diabetes would have yielded definitive evidence." (PMID 33958634, 2021). "In our study, PCSK9 inhibitor therapy markedly lowered LDL-C in both patients with and without diabetes irrespective of glycemic control." (PMID 33894772, 2021).
diabetes (continued). "However, PCSK9 inhibitors were primarily related to mild hyperglycaemias (n = 1587/87,724 (1.67%), adjusted ROR 1.48 (1.36–1.62)) rather than to diabetes (n = 372/87,724 (0.42%), adjusted ROR 0.67 (0.67–0.074))." (PMID 36383291, 2022). "Evidence gained from randomized controlled trials using PCSK9 inhibitors in secondary prevention suggests a similar efficacy on LDL-C reduction and clinical benefit in patients with diabetes mellitus compared to those without diabetes." (PMID 33894772, 2021). "Notably, the addition of PCSK9 inhibitors on top of HIS and ezetimibe, would be needed to achieve the targets in another 18% and 34% of patients with and without diabetes, respectively." (PMID 34271920, 2021). "Monoclonal antibodies to PCSK9, given every 2–4 weeks by subcutaneous injection, have been shown to reduce LDL-cholesterol by 50–60% compared with placebo in individuals with and without diabetes." (PMID 28025677, 2017). "To avoid the confounding effect of statins and to replicate the selection criteria of the OHGS cohort (non-diabetic), we measured plasma PCSK9 levels in 465 CAD cases and 357 controls without diabetes mellitus and not taking a statin or fibrate at the time of recruitment." (PMID 25180781, 2014). "Given the reported side effects associated with statins, the wider use of newer approaches to treat dyslipidaemia such as the PCSK-9 inhibitors and possibly, ethyl icosapent, may result in a further decrease in the CAD burden in both patient groups with and without diabetes." (PMID 34565341, 2021). "Furthermore, proprotein convertase subtilisin kexin type 9 (PCSK9) may have effects in lipid metabolism and β-cell function in T2DM, and use of anti-PCSK9 monoclonal antibodies has a potential to prevent new-onset diabetes in the future, although the evidence is currently lacking." (PMID 33672162, 2021).
hyperlipidemia (207 papers, 2013 to 2026). "Hyperlipidemia patients carrying this mutation will respond favorably to statins and PCSK9 inhibitor." (PMID 42109523, 2026). "In this study, PCSK9 is identified as a valuable biomarker for predicting the risk of hyperlipidemia in T2D patients, consistent with previous findings." (PMID 39951410, 2025). "This study aimed to combine clinical and laboratory indicators with PCSK9 to develop a predictive model for clinical application, specifically to identify the early clinical risk factors for the development of hyperlipidemia in T2D patients." (PMID 39951410, 2025). "Proprotein convertase subtilisin/kexin type 9 (PCSK9) inhibitors are a transformative therapy for patients with high cardiovascular risk or refractory hyperlipidemia, providing substantial LDL-C reduction and improving cardiovascular outcomes." (PMID 40422967, 2025). "In the following sections, we aimed to determine the effects of conditional knockdown of hepatic PCSK9 and the underlying mechanisms of action on modulating hyperlipidemia-induced chronic liver inflammation." (PMID 39963241, 2025). "All these findings suggest that the mechanisms of action of PCSK9 suppression on attenuating hyperlipidemia-induced inflammation are associated with downregulation of the MAPK signaling pathway." (PMID 39963241, 2025). "Participants with a history of hyperlipidemia or a fasting duration of <6 h were further excluded from the analyses of the associations between the lipid profiles, and PCSK9 levels." (PMID 41010058, 2025). "It has been reported that hyperlipidemia, a well-documented risk factors for cardiovascular diseases, tends increase platelet activation and PCSK9 expression." (PMID 37892538, 2023). "It has been confirmed that gain-of-function mutations of PCSK9 lead to increased risks of hyperlipidemia and ASCVDs, whereas loss-of-function mutations of PCSK9 reduced plasma levels of LDL-C and ASCVDs risk." (PMID 36970356, 2023). "Results obtained from a cross-sectional study in African American adults at risk of cardiovascular disease showed that TMAO induces hyperlipidemia through proprotein convertase subtilisin/kexin type 9 (PCSK9) and this pathway is mediated by IL-8." (PMID 36982880, 2023). "Statins and PCSK9 inhibitors both are imperative in the treatment of hyperlipidemia to reduce the risk of mortality and morbidity associated with CVDs." (PMID 36465767, 2022). "PCSK9 was originally characterized by its effects on lipid metabolism and PCSK9 inhibitors, and found to be effective in treating patients with hyperlipidemia and for reducing the risk of advanced cardiovascular events, including MI." (PMID 35207479, 2022). "Hyperlipidaemia is a major risk factor for cardiovascular diseases, and PCSK9 inhibition has emerged as a novel cholesterol-lowering therapy." (PMID 35854672, 2022). "In this manner, targeting PCSK9 is a novel attractive approach to reduce hyperlipidaemia and the risk for cardiovascular diseases." (PMID 34356856, 2021). "In the future, proprotein convertase subtilisin-kexin type 9 (PCSK9) inhibitors are expected to ameliorate hyperlipidemia due to genetic causes." (PMID 32078097, 2020). "PCSK9 inhibitors have been shown to not only reduce low-density lipoprotein (LDL) cholesterol levels in patients with hyperlipidaemia, but also lower the risk of cardiovascular events in patients with established cardiovascular disease." (PMID 30650126, 2019). "Humans with gain-of-function PCSK9 mutations have hyperlipidemia and heightened cardiovascular risk while those with loss-of-function mutations are protected from complications of atherosclerosis." (PMID 29084995, 2017).
hyperlipidemia (continued). "Second, we showed that PCSK9-deficiency is associated with reduced postprandial hyperlipidaemia in mice challenged with an olive oil bolus, due to decreased apoB output and a modification of chylomicron size, number and catabolism." (PMID 23298392, 2013). "Therefore, together with statin therapy, anti-PCSK9 antibodies are currently used for the clinical treatment of hyperlipidemia to decrease the risk of residual cardiovascular diseases (CVDs), a leading cause of death in humans." (PMID 39963241, 2025). "PCSK9 may be activated by elevated ox-LDL levels in the brain linked to hyperlipidemia, hence facilitating neuronal apoptosis via the NF-κB-Bcl-2/Bax-caspase 9-caspase 3 signaling pathways." (PMID 40354375, 2025). "Combination therapies integrating lipid-lowering agents like statins or PCSK9 inhibitors with anti-inflammatory drugs may offer a dual-action approach to cardiovascular risk reduction, addressing both hyperlipidemia and chronic vascular inflammation." (PMID 40217801, 2025). "Our findings indicate a potential pathway by which TMAO may promote hyperlipidemia—a CVD risk factor—through PCSK9." (PMID 36557234, 2022). "Because miR-483, a secretory miR, and circulatory levels of PCSK9 are increased in hyperlipidemic rodent models and human subjects, we investigated whether hyperlipidemia is associated with reduced levels of miR-483 in circulation." (PMID 33119548, 2020). "Since we showed that PCSK9-deficient mice have reduced post-prandial hyperlipidaemia following an oral fat load, we investigated whether an acute oral fat load can alter PCSK9 plasma concentrations in young healthy volunteers." (PMID 23298392, 2013). "Thus, controlling plasma PCSK9 levels in T2D patients may reduce the risk of hyperlipidemia and consequently lower cardiovascular risk." (PMID 39951410, 2025). "However, because PCSK9 deficiency is an extreme condition, the related studies with PCSK9-deficent models may have inaccurately predicted the role of PCSK9 in hyperlipidemia-induced inflammation." (PMID 39963241, 2025). "Because PCSK9 is mainly expressed in the liver and modulates lipid uptake through low-density lipoprotein receptor family members, the present study aimed to elucidate the effect of conditional knockdown of hepatic PCSK9 on hyperlipidemia-induced inflammation and the underlying mechanisms of action." (PMID 39963241, 2025). "Moreover, the insertion of two leucines in the signal peptide has been reported in a family with familial combined hyperlipidemia and two patients with FH and in vitro studies have shown that it causes a reduction in the secretion of the mature form of PCSK9 compared to the wild type PCSK9." (PMID 36061186, 2022). "Since the use of PCSK9 inhibitors has emerged outside conventional FH treatment strategies, their gradually increasing applications in clinical practice have not only brought good news to FH patients but also new hope for patients with hyperlipidemia that are at high risk of CAD." (PMID 33173529, 2020). "Isoquercetin, otherwise known as quercetin-O-beta-glucoside, is supplemented to a high cholesterol diet that could regulate expression and secretion of proprotein convertase subtilisin/kexin type 9 (PCSK9), reversing the hyperlipidemia and hyperinsulinemia caused by the diet." (PMID 32722185, 2020). "Among 269 participants, PCSK9 levels were significantly elevated in T2D patients with hyperlipidemia and exhibited a positive correlation with several lipid markers." (PMID 39951410, 2025). "Several approaches to PCSK9 blockade have been implemented for intervening hyperlipidemia in clinical practice." (PMID 41038958, 2025). "Third, although our work proposes ABCC4 inhibitor as a potential therapeutic target for hyperlipidemia, its synergistic effect with statins or PCSK9 inhibitors remains untested." (PMID 41038958, 2025).
hyperlipidemia (continued). "Our study is a systematic review and meta-analysis that assesses the efficacy and safety of a new PCSK9 antibody, tafolecimab, in hyperlipidemia." (PMID 40478366, 2025). "Conditional knockdown of hepatic PCSK9 remarkably decreased plasma levels of total cholesterol and alleviated hyperlipidemia-induced liver injury." (PMID 39963241, 2025). "Tafolecimab is a new member of the PCSK9 inhibitor family, a fully human immunoglobulin G2 (IgG2), developed as a treatment option in patients with hyperlipidemia." (PMID 40478366, 2025). "Current clinical medications for hyperlipidemia mainly include statins, fibrates, ezetimibe, PCSK9 inhibitors, and bile acid sequestrants." (PMID 40807276, 2025). "In summary, while tafolecimab demonstrates efficacy and safety comparable to other PCSK9 inhibitors in patients with hyperlipidemia, subtle differences exist in their potency and specific adverse event profiles." (PMID 40478366, 2025). "In models of hyperlipidemia or vascular disease, high PCSK9 levels exacerbate endothelial dysfunction, blood–brain barrier leakage, and neuroinflammation." (PMID 41465790, 2025). "Third, our results suggest that conditional knockdown of hepatic PCSK9 ameliorates hyperlipidemia-induced inflammation by downregulating multiple signaling pathways." (PMID 39963241, 2025). "Nearly 20% of the human population exhibit statin sensitivity including muscle lysis; in a search for new anti-hyperlipidemia therapies, PCSK9 inhibitors are being increasingly used." (PMID 40563926, 2025). "PCSK9 inhibition was initially approved in 2015 for adult patients with hyperlipidemia and in 2017 for people with cardiovascular disease and increased risk for myocardial infarction, stroke, and revascularization in atherosclerotic cardiovascular disease." (PMID 40732982, 2025). "In the T2D with hyperlipidemia group, PCSK9 exhibited a positive correlation with TC and disease duration, while demonstrating a negative correlation with hemoglobin." (PMID 39951410, 2025). "Second, we demonstrated that conditional knockdown of hepatic PCSK9 reduced hyperlipidemia-induced production of several pro-inflammatory cytokines." (PMID 39963241, 2025). "Current pharmacological interventions for hyperlipidemia include statins, fibrates, bile acid sequestrants, cholesterol absorption inhibitors, and proprotein convertase subtilisin/kexin type 9 (PCSK9) inhibitors." (PMID 40892857, 2025). "Herein, we report three potential drug-targeting proteins for hyperlipidemia: PCSK9, APOB, and NCAN." (PMID 39474612, 2024). "In recent years, PCSK9 has received more and more attention as a therapeutic target for hyperlipidemia." (PMID 38940622, 2024). "This provides clinicians with more comprehensive grounds and reasons for selecting PCSK9 inhibitors, especially for patients with a higher risk of AKI or those concurrently using nephrotoxic drugs due to hyperlipidemia." (PMID 39148544, 2024). "Two mAbs that neutralize PCSK9, Evolocumab and Alirocumab, have garnered approval from EMA and the US FDA for the clinical intervention of refractory hyperlipidemia, thereby paving the way for utilizing PCSK9 as a target in cancer therapy." (PMID 38185721, 2024).